RAX (retina and anterior neural fold homeobox)
Description:
Plays a critical role in eye formation by regulating the initial specification of retinal cells and/or their subsequent proliferation. Binds to the photoreceptor conserved element-I (PCE-1/Ret 1) in the photoreceptor cell-specific arrestin promoter.
Synonyms: RX; RAX1; MCOP3; MCOPS16
Tractability: No criterion of Open Targets' tractability assessment is met for any kind of drug.
Gene: Protein-coding gene on chromosome 18 (59,267,035 to 59,274,086, reverse strand). Ensembl gene ENSG00000134438.
Subcellular location: Nucleus
Gene Ontology:
Molecular function: DNA-binding transcription activator activity, RNA polymerase II-specific; RNA polymerase II cis-regulatory region sequence-specific DNA binding; sequence-specific double-stranded DNA binding; DNA-binding transcription factor activity, RNA polymerase II-specific; DNA binding
Biological process: positive regulation of transcription by RNA polymerase II; regulation of transcription by RNA polymerase II; visual perception; regulation of DNA-templated transcription
Cellular component: nucleus; chromatin
Genetic constraint (gnomAD): Loss-of-function variants: 12 observed, 16.24 expected, observed/expected ratio (o/e) 0.74, 90% interval 0.47 to 1.2. The upper end of that interval is the gene's LOEUF score, 1.2, which puts it in group 5 of 6, group 1 being the genes least tolerant of losing a copy. Missense variants: 527 observed, 466.33 expected, observed/expected ratio (o/e) 1.13, 90% interval 1.05 to 1.21. Synonymous variants: 276 observed, 230.25 expected, observed/expected ratio (o/e) 1.2, 90% interval 1.09 to 1.32.
Homologues: Orthologues: chimpanzee RAX (99% identical), macaque RAX (99% identical), dog RAX (94% identical), pig RAX (90% identical), mouse Rax (67% identical), rat Rax (67% identical), guinea pig RAX (61% identical). Paralogues in human: RAX2 (32% identical), ARX (31% identical), ALX4 (26% identical), OTP (25% identical), VSX2 (25% identical), PAX7 (24% identical), ALX3 (24% identical), SHOX2 (24% identical), PRRX1 (23% identical), PRRX2 (23% identical), UNCX (23% identical), PAX3 (22% identical), and 38 more.
Diseases named in the same sentence as RAX in open-access papers:
RAX is named in the same sentence as 27 diseases in open-access papers, as found by Europe PMC text mining. Sharing a sentence is not in itself a finding about the gene and the disease. The quoted sentences say what the papers report.
microphthalmia (15 papers, 2007 to 2026). Congenital or developmental anomaly in which the eyeballs are abnormally small. "Mutations in RAX, located on chromosome 18q21.32, account for approximately 2% of inherited anophthalmia/microphthalmia." (PMID 40038803, 2025). "Although human RAX mutations are associated with anophthalmia, microphthalmia, coloboma, and sclerocornea, the mechanisms by which these mutations cause human diseases are poorly understood." (PMID 37977220, 2023). "RAX mutations result in microphthalmia, whereas RAX2 mutations are associated with cone–rod dystrophy or age‐related macular degeneration." (PMID 32144893, 2020). "Few reports of RAX mutations in humans have been published, and these include anophthalmia, microphthalmia, and eye coloboma." (PMID 22736936, 2012). "RAX, located on chromosome 18q21.32, is linked to about 2% of inherited anophthalmia/microphthalmia." (PMID 18039390, 2007). "Mutations in the RAX gene were reported in human microphthalmia, anophthalmia, and sclerocornea." (PMID 37977220, 2023). "Additionally, previous studies showed that mutations in human OTX2 and RAX lead to anophthalmia, microphthalmia, and coloboma, findings that are in line with the eye phenotype upon bop1 knockdown in our study." (PMID 36007075, 2022). "Microphthalmia and coloboma are associated with RAX missense mutations." (PMID 22736936, 2012). "However, mutations in VSX2, CRYBA4, OTX2, and RAX have been detected in about 2%–3% patients with microphthalmia, anophthalmia, and coloboma." (PMID 20057906, 2009). "Likewise, mutations of the RAX gene were reported in human microphthalmia patients." (PMID 32144893, 2020). "Mutations in OTX2, RAX and CHX10, three genes expressed in the retina, are reportedly associated with anophthalmia/microphthalmia, possibly causing failure of retinal differentiation." (PMID 40038803, 2025). "Other genes have been identified as causing isolated anophthalmia or microphthalmia in humans (orthodenticle homeobox 2 [OTX2], retina and anterior neural fold homeobox [RAX], and CEH10 homeodomain-containing homolog [CHX10])." (PMID 21203406, 2010). "Knockdown of RAX during early eye development in Xenopus and zebrafish could lead to microphthalmia or anophthalmia while knockdown of it in mature retina could induce photoreceptor degeneration." (PMID 28831107, 2017). "OTX2, CHX10 and RAX have retinal expression and may result in anophthalmia/microphthalmia through failure of retinal differentiation." (PMID 18039390, 2007). "Mutations in several genes have been reported in patients with microphthalmia and/or coloboma, including BMP4 (OMIM 112262), VSX2 (CHX10; OMIM 142993), CRYBA4 (OMIM 123631), OTX2 (OMIM 600037), RAX (OMIM 601881), SIX6 (OMIM 606326), and SOX2 (OMIM 184429)." (PMID 20057906, 2009). "Seventy patients having non-syndromic forms of colobomatous microphthalmia (n=25), isolated microphthalmia (n=18), or anophthalmia (n=17), and syndromic forms of micro/anophthalmia (n=10) were included in this study after negative molecular screening for OTX2, RAX, SOX2, and CHX10 mutations." (PMID 21203406, 2010).
Anophthalmia (14 papers, 2007 to 2025). Absence of the globe or eyeball. "RAX mutations in humans have been reported, including anophthalmia, microphthalmia, and eye coloboma, in some cases associated with sclerocornea or severe cerebral malformation." (PMID 32111086, 2020). "While it is difficult to make firm conclusion, based on the published literature and our own unpublished data, BMP4 and RAX, in particular, appear to be very rare causes of anophthalmia." (PMID 24498598, 2013). "A novel missense RAX mutation was identified in three patients with bilateral anophthalmia and a distinct systemic and neurologic phenotype." (PMID 22736936, 2012). "This is the first report of a homozygous splicing RAX mutation associated with autosomal recessive bilateral anophthalmia." (PMID 22736936, 2012). "Cosegregation analysis in family A confirmed the previously suggested recessive inheritance of RAX mutations in human anophthalmia." (PMID 22736936, 2012). "Finally, in human, mutations in Rx/RAX lead to anophthalmia." (PMID 19229337, 2009).
coloboma (7 papers, 2009 to 2026). An abnormality in which a part of a structure in one or both eyes is missing. "In conclusion, combination of WES and homozygosity mapping identified a novel homozygous RAX mutation in a consanguineous family segregating with rarely reported asymmetrical coloboma." (PMID 28831107, 2017). "Moreover, a recent publication on heterozygous RAX mutation associated with ocular dysgenesis described a child with ocular coloboma only and no other associated malformations, suggesting again the mild or normal ocular phenotype that heterozygous RAX mutation carriers can harbor." (PMID 22736936, 2012).
diabetes (1 paper, 2014). "Upregulation at the early stages of diabetes with potential target the cellular activator of x cellular activator of PKR, RAX (PKR activator X), in retinal ganglion cells." (PMID 25268390, 2014).
Dystonia (1 paper, 2024). An abnormally increased muscular tone that causes fixed abnormal postures. "As the Prkralear-5J mouse exhibits dystonia, we next evaluated the presence of PACT/RAX in the cerebellum of developing wt (BTBR T+Itprtf/J) and Prkralear-5J mice." (PMID 39512178, 2024).
glioblastoma (1 paper, 2020). The most malignant astrocytic tumor (WHO grade IV). "Our previous results showed that RAX exerted an oncogenic factor in glioblastoma cells." (PMID 32015336, 2020).
Hyperglycemia (1 paper, 2024). An increased concentration of glucose in the blood. "According to this study, hyperglycemia-induced stress mediates RAX expression and deregulates RAX function." (PMID 38918766, 2024).
iris coloboma (1 paper, 2017). "In this study, we report a homozygous missense mutation in exon 1 of RAX in a patient with iris coloboma OS and optic disk coloboma OD, consistent with the hypothesis that mutations on both alleles could cause more severe phenotype." (PMID 28831107, 2017).
lens agenesis (1 paper, 2018). "SOX2 and PAX6 mutations may cause lens induction failure, FOXE3 mutations are associated with lens agenesis, and OTX2, CHX10, and RAX may cause failure of retinal differentiation." (PMID 30153864, 2018).
melanoma (1 paper, 2025). A malignant, usually aggressive tumor composed of atypical, neoplastic melanocytes. "Moving forward, clinical trial designs should selectively enrich for EMT-high and NCSC-high tumors such as melanoma and neuroblastoma, where RAX dependence is most pronounced." (PMID 41462674, 2025). "Second, it defines a biomarker-driven stratification schema: EMT-high/NCSC-high tumors, including melanoma, neuroblastoma, small-cell lung cancer, and subsets of pancreatic and triple-negative breast cancers, are predicted to be most RAX-dependent and thus therapeutically targetable." (PMID 41462674, 2025). "Clinically, tumors enriched in EMT/NCSC programs—such as melanoma, neuroblastoma, small-cell lung cancer, pancreatic ductal adenocarcinoma, and triple-negative breast cancer (TNBC)—represent RAX-dependent contexts." (PMID 41462674, 2025). "In melanoma, CD271 and SOX10 identify highly plastic, therapy-resistant, and metastasis-prone states, making this tumor type an archetype of RAX dependence." (PMID 41462674, 2025).
viral infection (1 paper, 2022). "Both PKR and RIG-I have been shown to be activated by RAX/PACT by varying stresses in a dsRNA-independent manner as well, and loss of RAX/PACT severely hampers PKR and RIG-I activation, even under conditions of viral infection where dsRNAs are plentiful." (PMID 35625664, 2022).
infection (3 papers, 2019 to 2024). The state of being infected such as from the introduction of a foreign agent such as serum, vaccine, antigenic substance or organism. "In comparison to the mock control, a similar reduction in the expression of RAX and SIX3 was detected in ectodermal cells after infection with both RV strains." (PMID 31405163, 2019).
cancer (1 paper, 2025). A tumor composed of atypical neoplastic, often pleomorphic cells that invade other tissues. "Emerging clinical evidence further highlights the translational relevance of EV-associated microRNAs in RAX-dependent cancers." (PMID 41462674, 2025). "Together, these converging data support the RAX hub as a multi-axis driver of cancer stemness, invasion, and resistance." (PMID 41462674, 2025). "The integration of adhesion, redox, and exosome–miRNA signaling within the CDH2-centered RAX hub converges on three malignant hallmarks: maintenance of cancer stemness, metastatic competence, and immune evasion." (PMID 41462674, 2025). "The CDH2-centered RAX hub provides an integrative framework unifying three previously disconnected axes of cancer biology: redox dynamics, adhesion signaling, and exosome-mediated communication." (PMID 41462674, 2025). "Importantly, systemic comorbidities such as diabetes converge on redox regulators including GPX4, linking metabolic stress to enhanced RAX reliance across multiple cancers." (PMID 41462674, 2025).
neurodegenerative disease (1 paper, 2023). A disorder of the central nervous system characterized by gradual and progressive loss of neural tissue and neurologic function. "Recent literatures reported that resveratrol could inhibit oxidation and apoptosis in neurodegenerative diseases through the Nrf2/HO-1, SIRT1, RAX/P-PKR, and JAK2/STAT3/PI3K/AKT/mTOR signaling pathways." (PMID 36836502, 2023).
tumor (1 paper, 2025). "Mechanistically, the RAX hub synthesizes findings from EMT/CSC biology, ferroptosis defenses, and exosome research into a self-reinforcing system that sustains tumor heterogeneity and stress resilience." (PMID 41462674, 2025). "Beyond tumor-intrinsic programs, CAFs—including populations arising from non-fibroblast lineages such as endothelial/perivascular cells, adipocytes, monocytes, and bone marrow-derived mesenchymal stem cells (MSC)—amplify RAX circuitry." (PMID 41462674, 2025).
RAX also shares sentences with these, for which no sentence is quoted: cyst (2 papers); cerebral malformation (1); developmental eye defect (1); Immunodeficiency (1); nematode infection (1); neuroblastoma (1); pancreatic ductal adenocarcinoma (1); retinal disease (1); retinoschisis (1); sclerocornea (1); small cell lung carcinoma (1); triple-negative breast carcinoma (1).